GRN (granulin precursor)
Diseases named in the same sentence as GRN in open-access papers (continued):
Sharing a sentence is not in itself a finding about the gene and the disease.
frontotemporal dementia (continued). "Additionally, mutations in the MAPT and GRN genes—commonly associated with frontotemporal dementia (FTD), a condition that disproportionately affects younger individuals—were analyzed." (PMID 40725212, 2025). "GRN is a pleiotropic growth factor with important roles in several physiological processes; GRN deficiency is associated with a broad range of pathological conditions affecting the brain, such as frontotemporal dementia." (PMID 38212481, 2024). "Loss-of-function mutations in the GRN gene are a cause of frontotemporal dementia and familial DLB." (PMID 38890280, 2024). "Patients with FTD due to GRN mutations (FTD-GRN) develop frontotemporal lobar degeneration with TDP-43 pathology type A (FTLD-TDP type A) and exhibit elevated levels of lysosomal proteins and storage material in frontal cortex, perhaps indicating lysosomal dysfunction as a mechanism of disease." (PMID 37118844, 2023). "Interestingly, GRN is also a candidate risk locus for frontotemporal dementia (FTD) and Parkinson’s disease (PD)." (PMID 37198259, 2023). "We propose that GRN mutations that cause PGRN deficiency inside neuronal lysosomes result in alkalinized lysosomal pH, decreased proteolytic activities, and impaired global protein homeostasis that eventually lead to frontotemporal dementia." (PMID 37974165, 2023). "Contemporary research showed GRN polymorphism is associated with schizophrenia and bipolar disorders, raising issues in favor of a shared pathophysiological basis behind the primary psychiatric disorders and frontotemporal dementia." (PMID 36160603, 2022). "Heterozygous GRN mutations cause frontotemporal dementia with parkinsonism." (PMID 34757540, 2022). "These may reflect the initial phases of the inflammatory environment and the vulnerability to demyelination and gliosis described in frontotemporal dementia patients with the GRN mutation." (PMID 36632182, 2022). "A fifth of frontotemporal dementia cases have autosomal dominant inheritance, most commonly due to hexanucleotide expansions in the chromosome 9 open reading frame 72 (C9orf72), mutations of granulin (GRN), or microtubule‐associated protein tau (MAPT) genes." (PMID 34133849, 2021). "Furthermore, mutations in the GRN gene have been linked to frontotemporal dementia and it has been proposed as a potential target for the treatment of those dementias." (PMID 34299022, 2021). "PGRN is encoded by the GRN gene, whose mutations can cause frontotemporal lobar degeneration and neuronal ceroid lipofuscinosis, but may potentially be also involved in the pathogenesis of Alzheimer’s disease." (PMID 32620998, 2020). "Indeed, pSAD-based minigenes have constituted an invaluable technology to functionally test variants of other disease genes such as GRN (Frontotemporal Dementia), SERPINA1 (Severe alpha-1 antitrypsin deficiency) and CHD7 (Charge Syndrome) genes." (PMID 31191615, 2019). "Similarly, mice with microglial deficiency of progranulin (GRN), a protein important for frontotemporal dementia, also displayed increased self-grooming." (PMID 31426845, 2019). "Loss of function mutations in progranulin (GRN) are a major cause of frontotemporal dementia (FTD)." (PMID 29929528, 2018). "Loss-of-function mutations in the progranulin (GRN) gene cause neurological disease in patients, typically frontotemporal lobar degeneration (FTLD) for heterozygous-null mutations, and neuronal ceroid lipofuscinosis (NCL) in the rare case of homozygous-null mutations." (PMID 29149899, 2017). "Progranulin gene (GRN) mutations are major causes of frontotemporal lobar degeneration." (PMID 28915852, 2017). "Mutations within the GRN gene cause frontotemporal lobar degeneration (FTLD)." (PMID 28358904, 2017). "In addition, evidence of lysosomal impairment has been recently found in brains from patients affected by frontotemporal lobar degeneration (FTLD) with accumulation of TDP-43 due to heterozygous loss-of-function mutations in the progranulin (GRN) gene." (PMID 27193329, 2016).
frontotemporal dementia (continued). "Haploinsufficiency of the human progranulin gene, GRN, causes frontotemporal dementia." (PMID 26248158, 2015). "By searching the genes coexpressed with PLD3 on COXPRESdb, we identified the human GRN gene encoding PGRN, whose mutation is responsible for frontotemporal lobar degeneration (FTLD) and neuronal ceroid lipofuscinosis, ranked as the second most significant gene coexpressed with PLD3." (PMID 25478031, 2014). "Pgrn has been described as a neurotrophic factor and inactivating GRN mutations cause frontotemporal lobar degeneration, which is a devastating neurological disease characterized by the presence of ubiquitinated inclusions of the transactivation response element DNA-binding protein-43." (PMID 24009671, 2013). "GRN mutations were first identified in 2006 as a cause of frontotemporal dementia (FTD) with TAR DNA-binding protein 43 (TDP-43) inclusions." (PMID 40234992, 2025). "The GRN gene, located on chromosome 17, is primarily associated with behavioral variant frontotemporal dementia (FTD), primary progressive aphasia (PPA), atypical parkinsonism, and corticobasal syndrome when mutations occur." (PMID 40725212, 2025). "Progranulin (GRN) mutations, most of which cause progranulin haploinsufficiency, are a major genetic cause of frontotemporal dementia (FTD)." (PMID 41178544, 2025). "Heterozygous mutations in the progranulin gene (GRN) are a key cause of frontotemporal dementia (FTD)." (PMID 38539243, 2024). "The silencing of one GRN allele is associated with an increased risk for Frontotemporal Dementia (FTD), but the silencing of both alleles results in Neuronal Ceroid Lipofuscinosis (NCL-11)." (PMID 39391322, 2024). "In humans, heterozygous GRN mutations cause frontotemporal dementia (FTD) due to progranulin haploinsufficiency." (PMID 36893203, 2023). "Heterozygous mutations in the GRN gene and hexanucleotide repeat expansions in C9orf72 are the two most common genetic causes of Frontotemporal Dementia (FTD) with TDP-43 protein inclusions." (PMID 36967384, 2023). "Loss of function progranulin (GRN) mutations are a major autosomal dominant cause of frontotemporal dementia (FTD)." (PMID 37118844, 2023). "In contrast to the lentiform TDP-43 NIIs, which are observed in certain frontotemporal dementias and which are conditional upon GRN or VCP mutations, our data support the hypothesis that the presence of α-Syn NIIs in MSA is instead purely amyloid-strain-dependent." (PMID 35327628, 2022). "The rs5848, a common GRN variant, was associated with an increased risk of AD, frontotemporal dementia (FTD), and Parkinson’s disease (PD)." (PMID 35085262, 2022). "Loss-of-function mutations in progranulin (GRN) are one of the most common genetic causes of frontotemporal dementia (FTD)." (PMID 34298019, 2021). "Heterozygous mutations in GRN lead to the development of frontotemporal dementia (FTD) and homozygous mutations cause the lysosomal storage disorder, neuronal ceroid lipofuscinosis." (PMID 33468204, 2021). "Clinically, heterozygous non-sense mutations of GRN that result in a loss of 50% of PGRN mRNA, cause FTD-GRN, a form of frontotemporal dementia that results from a progressive cortical atrophy and is, at present, almost always lethal." (PMID 35095393, 2021). "Facial Emotion Recognition (FER) and Faux Pas (FP) recognition tests were used to study social cognition within the Genetic Frontotemporal Dementia Initiative (GENFI), a large familial FTD cohort of C9orf72, GRN, and MAPT mutation carriers." (PMID 33221702, 2020). "Heterozygous, loss-of-function mutations in the granulin gene (GRN) encoding progranulin (PGRN) are a common cause of frontotemporal dementia (FTD)." (PMID 33028409, 2020). "The role of PGRN in AD has attracted attention in recent years since the discovery that mutations in GRN, the gene for progranulin, is one cause of frontotemporal dementia (FTD) resulting from frontotemporal lobar degeneration (FTLD)." (PMID 31864418, 2019).
frontotemporal dementia (continued). "However, in 2006, landmark studies showed that mutations in the GRN gene also underlie a familial form of frontotemporal lobar degeneration (FTLD) with distinct neuropathological features consisting of ubiquitin-positive protein aggregates in the nucleus and cytoplasm of cortical neurons." (PMID 30651094, 2019). "Interestingly, although a diagnosis of SD in association with a frontotemporal dementia genetic abnormality is rare, semantic impairment appears to develop quite commonly in individuals carrying a mutation in the GRN or microtubule associated protein tau (MAPT) genes." (PMID 27915998, 2016). "Dominant mutations in Progranulin (GRN) gene cause frontotemporal lobar degeneration (FTLD-GRN), whereas homozygous GRN mutations lead to neuronal ceroid lipofuscinosis, a childhood neurodegenerative disorder." (PMID 42302828, 2026). "Homozygous GRN mutations cause the lysosomal storage disorder (LSD) neuronal ceroid lipofuscinosis, whilst heterozygous mutations are associated with frontotemporal dementia (FTD-GRN)." (PMID 40200337, 2025). "Frontotemporal dementia is linked to mutations in the microtubule-associated protein tau (MAPT), progranulin (GRN), and chromosome 9 open reading frame 72 (C9orf72) genes." (PMID 41194168, 2025). "To date, among a cohort of 97 unrelated patients with frontotemporal lobar degeneration characterized by TAR DNA-binding protein 43-kDa-positive inclusions (FTLD-TDP), fifty distinct GRN mutations have been identified." (PMID 41373403, 2025). "Pathogenic GRN variants that reduce progranulin (PGRN) levels cause frontotemporal dementia (FTD)." (PMID 41373403, 2025). "Heterozygous mutations in the GRN gene lead to reduced levels of progranulin (PGRN), causing frontotemporal dementia (FTD) characterized by frontotemporal lobar degeneration (FTLD) with TAR DNA-binding protein 43 (TDP-43) inclusions." (PMID 41373403, 2025). "All AD-related syndromes where the primary pathology was not AD did have AD present as a copathology, except for 2 LOAD cases (Pick disease and chronic traumatic encephalopathy) and 1 EOAD case with FTLD-TDP-A related to a pathogenic variant in the GRN gene." (PMID 39928343, 2025). "Studies on mice with GRN haploinsufficiency show an excessive removal of synapses in the cortex, along with behavioral abnormalities that resemble frontotemporal dementia." (PMID 41169352, 2025). "While pathogenic MAPT mutations are well-characterized within exons 9–13, and most GRN CNVs are known to cause haploinsufficiency in frontotemporal dementia, the specific roles of CNVs in MAPT exon 8 and GRN exon 6 remain poorly defined." (PMID 40725212, 2025). "This L-R binding was first identified in the brain, underscores SORT1’s role in mediating rapid endocytosis and lysosomal localization of GRN, central in the development of inherited frontotemporal lobar degeneration." (PMID 39143467, 2024). "Growing evidence has suggested the pivotal role of microglia in the disease pathogenesis of frontotemporal dementia with GRN mutations, and studies have indicated that Grn−/− microglia accumulate significantly more lipids." (PMID 38191490, 2024). "It was identified as a contributing factor to frontotemporal lobar degeneration (FTLD), particularly in individuals with progranulin (GRN) mutations." (PMID 39872397, 2024). "Genetic variants in TMEM106B are a common risk factor for frontotemporal lobar degeneration (FTLD) and the most important modifier of disease risk in patients with progranulin (GRN) mutations (FTLD-GRN) identified as early as 2010." (PMID 36707901, 2023). "In this subset of frontotemporal lobar degeneration with TDP-43 inclusions (FTLD-TDP), patients have a heterozygous loss-of-function mutation in GRN, resulting in haploinsufficiency of the secreted protein progranulin." (PMID 36919702, 2023). "Haploinsufficiency of GRN causes frontotemporal dementia (FTD)." (PMID 36207292, 2022).
frontotemporal dementia (continued). "Clinical and genetic overlap exists with frontotemporal dementia (FTD), which is caused by mutations in C9orf72, MAPT, GRN, TARDPB, VCP, as well as other genes." (PMID 35493319, 2022). "Two of the novel AD loci (TMEM106B, GRN) are also known frontotemporal dementia (FTD) genes, suggesting their potential roles in protein clearance rather than in specific disease-related protein aggregates." (PMID 34935119, 2022). "Genetic variation at the TMEM106B locus has been identified as a risk factor for frontotemporal lobar degeneration with TDP-43 inclusions (FTLD-TDP), especially for individuals with granulin (GRN) gene mutations." (PMID 35344985, 2022). "The TMEM106B and GRN signals in frontotemporal lobar degeneration with TAR DNA-binding protein (TDP-43) inclusions (frontotemporal lobar degeneration TDP) probably share causal variants with ADD (coloc PP4 = 99.8% and coloc PP4 = 80.1%, respectively)." (PMID 35379992, 2022). "Impaired lysosomal proteolysis and decreased activity of the lysosomal enzyme cathepsin D were reported in fibroblasts lysates in heterozygous GRN mutation carriers and in iPSC-derived human cortical neurons in frontotemporal dementia (FTD) patients harboring GRN mutations." (PMID 36142612, 2022). "Most notably, the understanding of frontotemporal dementia has been further advanced by the identification of disease causing mutations in the genes for TAR DNA-binding protein-43 (TARDBP), progranulin (GRN) and C9orf72-SMCR8 complex subunit (C9ORF72)." (PMID 35120450, 2022). "They identified the histone deacetylase inhibitor suberoylanilide hydroxamic acid (SAHA) as an enhancer of GRN expression and validated their results in cells from patients with frontotemporal dementia." (PMID 34366786, 2021). "In 2006, it was demonstrated that pathogenic progranulin (GRN) mutations can cause autosomal dominant Frontotemporal dementia (FTD), histopathologically characterised by aggregation of ubiquitin-binding protein p62 and phosphorylated TAR DNA-binding protein 43 (pTDP-43) in the frontal cortex." (PMID 34344473, 2021). "In this cohort study of 232 patients with genetic frontotemporal dementia, patients with MAPT variants showed the highest frequency and severity of most behavioral symptoms compared with C9orf72 and GRN carriers." (PMID 33404617, 2021). "First, PGRN haploinsufficiency resulting from mutations in the GRN gene, is one of the major causes of frontotemporal lobar degeneration (FTLD) with TDP-43 positive inclusions." (PMID 34103390, 2021). "Genetic variants in Granulin (GRN), which encodes the secreted glycoprotein progranulin (PGRN), are associated with several neurodegenerative diseases, including frontotemporal lobar degeneration, neuronal ceroid lipofuscinosis, and Alzheimer’s disease." (PMID 34618685, 2021). "Haploinsufficiency of the progranulin (PGRN) protein, due to heterozygous mutations in the granulin (GRN) gene, is a leading cause of frontotemporal lobar degeneration with TDP‐43 aggregates (FTLD‐TDP)." (PMID 32852886, 2020). "Consistent with the progressive dysexeutive syndrome patients, GRN mutation carriers have been shown to have more complaints on executive functions and less complaints on social changes than other ubiquitin-positive Frontotemporal dementia (FTD)." (PMID 33216842, 2020). "In a study of frontotemporal dementia (FTD), symptomatic FTD patients with GRN mutation had more WMH load than patients with microtubule-associated protein tau (MAPT) and chromosome 9 open reading frame 72 (C9orf72) gene mutations." (PMID 33352859, 2020). "Patients with frontotemporal dementia (FTD) resulting from granulin (GRN) haploinsufficiency have reduced levels of progranulin and exhibit dysregulation in inflammatory and lysosomal networks." (PMID 32792571, 2020). "Progranulin (GRN) was determined to be a genetic regulator of LDAM formation and loss-of-function mutations in GRN are a cause of frontotemporal dementia." (PMID 32823544, 2020).
frontotemporal dementia (continued). "Heterozygous mutation of the GRN gene is the major cause of FTD-TDP, which is a subtype of frontotemporal dementia (FTD) characterized by ubiquitinated and fragmented TAR-DNA binding protein-43 (TDP-43)." (PMID 31775776, 2019). "Recently, it has been demonstrated in the Genetic Frontotemporal Dementia Initiative (GENFI) study that gray matter and cognitive changes can be identified 5–10 years before the expected onset of symptoms in adults at risk of genetic FTD, including a cohort carrying GRN mutations." (PMID 29146050, 2018). "Haploinsufficiency of GRN, the gene encoding PGRN, results in 50% depletion of PGRN protein levels, and causes frontotemporal dementia (FTD), an early onset form of dementia." (PMID 28358904, 2017). "Haploinsufficiency of GRN, the gene encoding progranulin (PGRN), causes frontotemporal lobar degeneration (FTLD), the second most common cause of early-onset dementia." (PMID 28743268, 2017). "PGRN deficiency is associated with neurodegeneration and frontotemporal dementia (FTD), mainly due to mutation in GRN." (PMID 26697121, 2015). "Individuals carrying a null or loss-of-function allele in GRN, the gene encoding PGRN, suffer from PGRN haploinsufficiency, which is a major cause of the most common pathological subtype of FTD, frontotemporal lobar degeneration (FTLD-TDP)." (PMID 24163244, 2014). "Heterozygous loss-of-function mutations in the GRN gene are a major cause of hereditary frontotemporal dementia, and there is currently no treatment." (PMID 39033178, 2024). "Genome-wide association studies (GWAS) identified mutations of the TMEM106B gene as a major risk factor for frontotemporal lobar degeneration with TDP-43 pathology (FTLD-TDP), which was mostly associated with the risk of FTLD-TDP in patients with progranulin (GRN) mutations." (PMID 38710967, 2024). "The interaction of NCAM2 with Granulin, GRN, one of the principal proteins associated with familial frontotemporal dementia, suggest a plausible role of NCAM2 as a receptor of the protein and a possible implication in frontotemporal dementia." (PMID 34576185, 2021). "The neuropathology observed in patients bearing progranulin (GRN) loss-of-function (LOF) mutations is dictated by a gene dosage-dependent effect, with most haploinsufficient individuals developing an early-onset form of frontotemporal dementia (FTD-GRN)." (PMID 33795008, 2021). "For example, several genes causing ALS and/or frontotemporal dementia (C9orf72, VCP, SQSTM1, OPTN, UBQLN2, GRN, CHMP2B) affect the autophagic machinery; and some Alzheimer’s Disease genes (APOE, TREM2, CD33, ABCA7) are preferentially or exclusively expressed in microglia." (PMID 33892821, 2021). "In 1998, frontotemporal dementia associated with parkinsonism was linked to chromosome 17 (FTDP-17), leading to the discovery of the microtubule-associated protein tau gene (MAPT) in 1998 and of the progranulin gene (GRN) in 2006." (PMID 29370838, 2018). "GRN is associated with frontotemporal lobar degeneration, and microglia lacking GRN are shown to have an aberrant expression profile at 18 but not at 4 months of age." (PMID 28539882, 2017). "In addition, mutations in the frontotemporal lobar degeneration (FTLD) genes – the microtubule-associated protein tau (MAPT), granulin (GRN) – have also been found to be associated with clinical AD." (PMID 25333068, 2014). "Given the significant overlap in clinical presentation, individuals with a strong family history of AD should also be screened for mutations in MAPT and GRN, genes typically associated with frontotemporal lobar degeneration, when no autopsy is available." (PMID 22312439, 2012). "In aged mice, GRN knockout mice (a model for frontotemporal dementia, FTD), and brain tissues from normal human aging, researchers have identified a special subpopulation of microglia: lipid-droplet-accumulating microglia (LDAM)." (PMID 40722268, 2025).